RNU6-128P (RNA, U6 small nuclear 128, pseudogene)
Gene: Small nuclear RNA gene on chromosome 4 (158,794,590 to 158,794,696, reverse strand). Ensembl gene ENSG00000206703.
Homologues: Orthologues: chimpanzee U6 (100% identical), macaque U6 (95% identical), mouse Gm25801 (93% identical), rat U6 (93% identical), pig U6 (91% identical), guinea pig U6 (88% identical), guinea pig U6 (85% identical). Paralogues in human: RNU6-144P (93% identical), RNU6-21P (93% identical), RNU6-1 (92% identical), RNU6-15P (92% identical), RNU6-2 (92% identical), RNU6-20P (92% identical), RNU6-26P (92% identical), RNU6-3P (92% identical), RNU6-45P (92% identical), RNU6-4P (92% identical), RNU6-5P (92% identical), RNU6-6P (92% identical), and 1289 more.